SNORD115 (Small nucleolar RNA SNORD115 )
Synonyms: LOC124902571
Gene: Small nucleolar RNA gene on chromosome 10 (29,575,306 to 29,575,381, forward strand). Ensembl gene ENSG00000212411.
Gene Ontology:
Biological process: RNA processing
Cellular component: nucleolus
Homologues: Orthologues: chimpanzee SNORD115 (100% identical), macaque SNORD115 (88% identical), pig SNORD115 (64% identical), rabbit SNORD115 (64% identical). Paralogues in human: SNORD115-48 (84% identical), SNORD115-35 (83% identical), SNORD115-16 (80% identical), SNORD115-3 (80% identical), SNORD115-11 (79% identical), SNORD115-13 (79% identical), SNORD115-29 (79% identical), SNORD115-36 (79% identical), SNORD115-38 (79% identical), SNORD115-39 (79% identical), SNORD115-43 (79% identical), SNORD115-10 (78% identical), and 37 more.
Diseases named in the same sentence as SNORD115 in open-access papers:
SNORD115 is named in the same sentence as 16 diseases in open-access papers, as found by Europe PMC text mining. Sharing a sentence is not in itself a finding about the gene and the disease. The quoted sentences say what the papers report.
Prader-Willi syndrome (8 papers, 2013 to 2024). "The loss of SNORD115 expression is a pivotal genetic factor leading to the development of Prader-Willi syndrome (PWS)." (PMID 39118131, 2024). "Alternate splicing of the serotonin 2C receptor (5-HT2CR) is negatively regulated by the Snord115, loss of which is seen in most patients with Prader-Willi syndrome (PWS)." (PMID 27931246, 2016). "While there is evidence to consider the altered expression of SNORD115 and SNORD116, a primary cause of Prader-Willi syndrome, most recently those two and some other snoRNAs, has been implicated in the pathogenesis of schizophrenia." (PMID 31888770, 2019). "The small nucleolar RNA 115 (SNORD115), another paternally imprinted gene located in the Prader-Willi Syndrome (PWS) region of chromosome 15, was hypermethylated by 16%." (PMID 30779748, 2019). "Processing of Htr2c pre-RNA is mediated, in part, by the actions of the small nucleolar RNA (snoRNA) Snord115 (previously h/mbii-52) present within the imprinted Prader-Willi syndrome (PWS) locus." (PMID 27931246, 2016).
Angelman syndrome (3 papers, 2023 to 2026). A neurogenetic disorder characterized by severe intellectual deficit and distinct facial dysmorphic features. "We sought to assess the efficacy of Ube3a-as ASO and Snord115 ASO in our new mouse model of Angelman syndrome across brain regions and over time by systematically determining the total Ube3a protein, Ube3a mRNA, and Ube3a-ATS levels." (PMID 36594817, 2023).
joint disease (2 papers, 2019 to 2021). "Changes in the methylation levels of genes associated with skin/joint disease (MBP, OSBPL5, SNORD115, and HCG26) and joint disease (IL22, ELF5, PPP2R2D, PTPRN2, and HCG26) were found." (PMID 33869291, 2021). "Biological inference prioritized notable DMRs associated with skin disease (SIGLEC14, JAM3, PCOLCE, RXRB), skin and/or joint disease (MBP, OSBPL5, SNORD115, HCG26), and joint disease (IL22, ELF5, PPP2R2D, PTPRN2, HCG26)." (PMID 30779748, 2019). "Although few DMRs exceeded a 10% change in methylation, it is noteworthy that many of those which did play roles in the pathogenesis of skin disease (SIGLEC14, JAM3, PCOLCE, RXRB, ELF5, IL22), joint disease (MBP, HCG26, IL22, PPP2R2D, PTPRN2) or are known to be imprinted (OSBPL5, SNORD115)." (PMID 30779748, 2019).
Obesity (2 papers, 2016 to 2020). Accumulation of substantial excess body fat. "Finally, and in the same vein, loss of SNORD115 might only become apparent under perturbed metabolic contexts, perhaps as ‘secondary disease-effects’ once obesity is fully established in individuals with PWS." (PMID 33016258, 2020). "During the course of diet-induced obesity, body weight gain of Snord115-KO mice was similar to WT mice with normal adiposity as evidenced by the weights of perigonadal, subcutaneous fat mass and liver measured after euthanasia." (PMID 33016258, 2020).
schizophrenia (2 papers, 2018 to 2019). A major psychotic disorder characterized by abnormalities in the perception or expression of reality. "It is significant that the RNA-Seq study that showed changes in SNORD115 and SNORD116 expression in females with schizophrenia also showed changes in the levels of the snoRNA U2, a component of the spliceosome that removes intronic sequences from precursor-mRNA in females with schizophrenia." (PMID 29657307, 2018). "To date, the way SNORD115 and SNORD116 mediate their effect in schizophrenia is not clear." (PMID 29657307, 2018).
Alzheimer disease (1 paper, 2024). A progressive, neurodegenerative disease characterized by loss of function and death of nerve cells in several areas of the brain leading to loss of cognitive function such as memory and language. "SNORD115 and SNORD116 dysregulation is noted in Alzheimer’s disease (AD) as well, affecting RNA processing and protein synthesis, leading to neuron dysfunction and cognitive decline." (PMID 39000310, 2024).
anxiety disorder (1 paper, 2020). A category of psychiatric disorders which are characterized by anxious feelings or fear often accompanied by physical symptoms associated with anxiety. "Because altered HTR2C signaling, including abnormal RNA editing, is linked to anxiety disorders and depressive states, we first subjected a cohort of 8–12 week-old Snord115-deficient and WT mice to the open field (OF) test." (PMID 33016258, 2020).
psychosis (1 paper, 2022). "Other genes and snoRNAs that might play a role in the onset of psychosis are GABRG3, NDN, CYFIP1 and SNORD115." (PMID 35887798, 2022).
cancer (1 paper, 2018). A tumor composed of atypical neoplastic, often pleomorphic cells that invade other tissues. "We identified SFRP1 and snoRNAs (especially SNORD115 and SNORD114) as the initial regulators of cancer progression, accompanied by significant changes in extracellular matrix organization." (PMID 30647841, 2018).
genetic disorder (1 paper, 2018). "Yet, there is mounting evidence to suggest an adjunctive role of SNORD115 in this genetic disorder." (PMID 29572515, 2018).
SNORD115 also shares sentences with these, for which no sentence is quoted: embryonic carcinoma (2 papers); Anxiety (1); Cognitive impairment (1); leukemia (1); liver cancer (1); morbid obesity (1).